INS (insulin)
Diseases named in the same sentence as INS in open-access papers (continued):
Sharing a sentence is not in itself a finding about the gene and the disease.
diabetes (continued). "Circulating levels of interleukin-6 (IL-6) are raised in insulin resistant states such as obesity, impaired glucose tolerance (IGT), and type 2 diabetes mellitus (DM)." (PMID 17374166, 2007). "Insulin-treated patients who had complications of diabetes had worse Negative Well-being, Energy, and total General Well-being than insulin-treated patients who had no complications of diabetes." (PMID 16817960, 2006). "During the first 48 hours after surgery, insulin was administrated to four patients with known diabetes mellitus and to five patients without diabetes mellitus, but insulin administration could not be retraced in one patient with known diabetes mellitus." (PMID 15566589, 2004). "Thus, insulin does not lower blood sugar levels to the extent that it does in people without diabetes." (PMID 15706798, 1998). "Consequently, we could not accurately assess the severity of diabetes, although we extracted information on insulin use to approximate it as best as possible." (PMID 40864338, 2026). "In addition, except diabetes medication, we did not consider other diseases or medications that could affect insulin resistance or insulin function." (PMID 41003141, 2025). "In contrast, type 2 diabetes mellitus (T2DM) is the more common DM, accounting for up to 90% of cases, and is attributed to a lack of insulin secretion, impaired insulin action, or both." (PMID 40510419, 2025). "A core feature of diabetes mellitus (DM) is the disorder of glucose and lipid metabolism, mainly due to the lack of insulin or insufficient insulin action leading to the disorder of carbohydrate metabolism, resulting in hyperglycemia and urine sugar." (PMID 40650120, 2025). "However, it is important to bear in mind that patients on insulin therapy generally have more severe diabetes than those not taking insulin, what may ultimately introduce some bias in these observations." (PMID 41146261, 2025). "GIP stimulates also glucose-dependent insulin release in people without diabetes and may have a role in appetite regulation: despite mixed findings, preclinical research suggests that the addition of GIP RA may enhance appetite suppression and WL associated with a fixed-dose of GLP-1 RA." (PMID 40741227, 2025). "However, despite average diabetes duration of >10 years in patients with type 1 and type 2 diabetes, 63% and 18% of patients, respectively, did not proactively adjust insulin therapy and/or notify their healthcare provider with worsening glucose control prior to DKA presentation." (PMID 40940823, 2025). "Unlike DKA due to type 1 diabetes mellitus (T1DM), where absolute insulin deficiency is the hallmark, PCC-induced DKA is driven by extreme catecholamine excess causing profound insulin resistance, impaired insulin secretion, and enhanced counter-regulatory hormone activity for a long duration." (PMID 40584808, 2025). "I didn’t get any explanation at the health facility that the diabetes may become a problem...[the doctor] knew I had diabetes, but the insulin injection was not given to me...[MDR-TB] could have been avoided if I knew that I had to keep the diabetes under control." (PMID 41314841, 2025). "Moreover, since our population consisted of insulin‐treated patients with a long duration of diabetes, we cannot rule out the possibility that a small percentage of undiagnosed LADA cases may be present among them." (PMID 40277315, 2025). "However, our findings suggest that increased levodopa uptake may transiently stimulate insulin secretion, co-released with dopamine, particularly in individuals with obesity but without diabetes." (PMID 40099262, 2025). "However, the abrupt onset of metabolic decompensation, close temporal relationship to ICI dosing, and prolonged insulin-requiring hyperglycemia in the presence of low c-peptide or positive antibodies were not in keeping with steroid-induced diabetes and instead aligned with CIADM." (PMID 41450393, 2025).
diabetes (continued). "However, numerous clinical trials show no or beneficial effects on critical diabetes biomarkers such as glycated hemoglobin, blood glucose, and blood insulin; these studies do not support the IARC hypothesis." (PMID 41038346, 2025). "Finally, the binary definition of eligibility for diabetes remission used did not incorporate measures of β‐cell function or insulin resistance; incorporating such metrics may have led to different results." (PMID 40707395, 2025). "We hypothesized that a higher dose of dexamethasone would increase PG levels and the risks of hyperglycemic (PG ≥ 11.1 mmol/L) and severe hyperglycemic (PG ≥ 20 mmol/L) events, as well as more insulin use compared to the standard dose of dexamethasone regardless of baseline diabetes status." (PMID 40665171, 2025). "For example, one study showed that men with type 2 diabetes, both not on medication and on insulin, have increased prostate cancer mortality, suggesting that a poorly controlled metabolic state of diabetes may contribute to prostate cancer progression and disease aggressiveness." (PMID 40558296, 2025). "In studies using insulin, the chances of having a baby large for gestational age or with respiratory distress syndrome or neonatal jaundice or requiring admission to the neonatal intensive care unit were higher in women with gestational diabetes mellitus than in those without diabetes." (PMID 40238398, 2025). "Moreover, in the context of diabetes—a metabolic disorder marked by impaired glucose, lipid, and protein metabolisms due to insufficient insulin production and islet cell dysfunction—PVA hydrogels modified with glycerol have shown promise for prolonged insulin release." (PMID 40871151, 2025). "Continuous exogenous insulin therapy stands as the prevailing treatment modality for individuals afflicted with T1DM, but exogenous insulin does not mimic normal endogenous insulin secretion in the body and may not even control the development of diabetes and its consequences." (PMID 40860518, 2025). "Type 2 diabetes (T2-DM) is a non-insulin-dependent condition characterized by inadequate production and peripheral resistance to insulin." (PMID 39946391, 2025). "Hypoglycemia can also occur in people without diabetes, along with certain diseases and conditions, such as insulinoma, adrenal insufficiency, liver or kidney dysfunction, and postprandial hypersecretion of insulin, a phenomenon referred to as reactive hypoglycemia." (PMID 41367919, 2025). "Diabetes mellitus type 2 (T2-DM) is one of the most prevalent chronic metabolic diseases, marked by insulin resistance and a relative lack of insulin production." (PMID 40195395, 2025). "Therefore, it could be that our cohort without known diabetes had so marginal differences in insulin resistance that we were not able to find them with surrogate measures for insulin sensitivity." (PMID 39911868, 2025). "Exploring its impact across different patient profiles, such as oncologic versus non-oncologic individuals, various types of diabetes, insulin use, or baseline CRP, could provide valuable insights into how these treatments influence muscle decline in distinct pathophysiological contexts." (PMID 41156461, 2025). "Regardless of the type of diabetes, the result is an inability of tissues to access the circulating pool of energy residing within carbohydrates that classically drives aerobic oxidation, and thus the insulin-sensitive tissues (such as skeletal muscle) experience starvation." (PMID 40429969, 2025). "Type 2 diabetes mellitus (T2DM) is characterized by insulin resistance in peripheral tissues like skeletal muscle, liver, and fat tissue, which may also affect the brain, coupled with inadequate compensatory insulin release from pancreatic β-cells, culminating in persistent hyperglycemia." (PMID 40933306, 2025).
diabetes (continued). "However, pegvisomant exerts a favorable effect on carbohydrate metabolism in patients with acromegaly, including those with diabetes, by decreasing fasting glucose and HbA1c levels, as well as improving insulin sensitivity, which is beneficial for patients both with and without diabetes." (PMID 40142714, 2025). "However, our findings revealed that elevated uric acid levels were not positively related to high Glu and low insulin levels in STZ-induced diabetic hamsters, which indicated that uric acid accelerated but did not cause diabetes by inhibiting islet β-cell survival." (PMID 41012372, 2025). "For instance, while “insulin” may be a predictive term for the disease “diabetes”, it is not suitable as evidence for coding according to the WHO guidelines and educational textbooks as insulin can be prescribed for various medical conditions other than diabetes." (PMID 39935026, 2025). "Additionally, the directionality of association remained consistent before and after adjustment, suggesting that insulin therapy may attenuate rather than reverse the impact of diabetes on telomere dynamics." (PMID 40299325, 2025). "However, some studies suggest that insulin therapy can improve sperm content and motility, while others find that semen volume may or may not be affected by diabetes." (PMID 40687580, 2025). "While insulin non-adherence was the most common cause in patients with known type 1 diabetes, drugs associated with cancer related treatments emerged most common precipitating factor for DKA in cancer patients with underlying type 2 diabetes or drug induced diabetes." (PMID 40940823, 2025). "Furthermore, while this study provides valuable insights into mRNA expression patterns, it is important to note that the potential confounding effects of diabetes treatments, such as metformin, sulfonylureas, and insulin, on mRNA expression cannot be entirely ruled out." (PMID 40004948, 2025). "Although synthetic oral hypoglycemic agents and insulin injections are common methods of managing diabetes, they do not seem to be able to completely prevent the development of diabetes complications and sometimes their side effects may exacerbate the condition." (PMID 40076380, 2025). "Type 1 diabetes is the major type of diabetes in childhood; in 2024, over 1.81 million children and adolescents, younger than 20 years, had type 1 diabetes, but it can occur at any age, it cannot be prevented, and patients with type 1 diabetes require insulin to survive." (PMID 41012462, 2025). "Diabetes mellitus (DM) is a metabolic disorder characterized by elevated blood glucose levels due to a lack of insulin secretion, function, or both." (PMID 40140841, 2025). "They demonstrated that a single administration of AAV1 co-expressing insulin and glucokinase in skeletal cells could maintain dogs (n = 6) with diabetes in a normoglycemic state for over 8 years without hypoglycemic episodes (HbA1c ≤ 6.5%), while also preventing secondary complications." (PMID 40869431, 2025). "Given that insulin constitutes a pivotal element in regulating glucose homeostasis, thereby understanding the mechanisms by which GABA influences its secretion may produce significant implications for the management and therapeutic approaches related to diabetes." (PMID 40149935, 2025). "DM is characterized by either a lack of insulin production (type 1 diabetes) or insulin resistance (type 2 diabetes), both of which contribute to a state of hyperglycemia, or high blood sugar." (PMID 40572277, 2025). "The most important one is diabetes mellitus (DM), an endocrine disorder characterized by the absence of insulin (type 1 DM; DM1) or the inability of cells to respond to it (type 2 DM; DM2)." (PMID 38737201, 2024). "Diabetes during pregnancy occurs in subjects who are unable to compensate for insulin insensitivity with adequate insulin secretion and who have never had a positive history of DM prior to gestation." (PMID 38617398, 2024).
diabetes (continued). "However, recent studies have proven otherwise as intracellular insulin paucity (characteristic of both type 1 and 2) is what leads to low levels of CYP7B1 and the accumulation of toxic cholesterol metabolites, explaining the existence of MASLD progression with both types of diabetes." (PMID 38591148, 2024). "While reduced insulin sensitivity is a key metabolic disturbance linked to MASLD37,38, a large retrospective cohort study has underscored that a history of GDM, independent of insulin resistance or diabetes, constitutes an independent risk factor for the development of MASLD36." (PMID 38918525, 2024). "However, the incidence of other diabetes complications, such as retinopathy, nephropathy, and neuropathy, was significantly higher among patients who were on insulin compared to those not on insulin (50.7 % versus 27.5 %; p = 0.005)." (PMID 39295783, 2024). "Thus, in the absence of other possible causes of diabetes, it seems reasonable to hypothesize a role of the identified ABCC8 gene variants in such insulin secretory dysfunction." (PMID 38980630, 2024). "Diabetes mellitus (DM) is a chronic condition that is characterized by a lack of insulin, high blood sugar levels, dyslipidemia, and impaired nephrotic function." (PMID 38640098, 2024). "Diabetes mellitus (DM) is a chronic metabolic disorder that occurs when pancreatic β‐cells can no longer produce enough insulin to maintain normal blood glucose levels." (PMID 39505716, 2024). "Approximately 90% of all DM cases are type 2 diabetes (T2D), characterized by insulin resistance, in which the body does not fully respond to insulin, making it the most prevalent type." (PMID 39620004, 2024). "The primary classifications of diabetes typically encompass type 1 diabetes, characterized by insulin dependence resulting from immune-mediated destruction of β cells, and type 2 diabetes, characterized by non-insulin dependence stemming from an insulin secretory defect and insulin resistance." (PMID 38715052, 2024). "In addition, improvement in insulin sensitivity in response to scopoletin (1 mg/kg/day, p.o.)can activate the AMPK and the IRS1–PI3K–Akt pathways in pancreatic β cells of high-fructose diet (HFHFD) rats and improves glucose homeostasis in HFHFD-induced diabetes rats." (PMID 38464713, 2024). "The study found that a high carbohydrate diet would not improve the insulin sensitivity of non-diabetes subjects, because monounsaturated fatty acids and polyunsaturated fatty acids could reduce the level of low-density lipoprotein cholesterol, but would not have adverse effects." (PMID 39596859, 2024). "Stable graft function and insulin secretion were observed in NHP models of diabetes and human patients who received βAir containing porcine islets and human islets respectively, both in the absence of immunosuppressants, though complete insulin independence was not achieved." (PMID 38650946, 2024). "The purpose of this study was to investigate whether insulin sensitivity and β-cell function deteriorate after the age of 65 years and the factors contributing to the exacerbation of glucose tolerance with aging among older adults with no history of diabetes." (PMID 38188453, 2024). "Comparing GLP-1RA with basal insulin, a GLM class recently observed not to be associated with pancreatic cancer risk, ensures comparison of patients who require second-line therapy and avoids their comparison with patients requiring less intensive therapy for their diabetes." (PMID 38175642, 2024). "Participants were categorized into four groups based on glucose metabolism state: normal glucose regulation (NGR), prediabetes (pre-DM), diabetes mellitus (DM) without insulin prescribed (Rx), and DM with insulin Rx." (PMID 39003471, 2024).
diabetes (continued). "This article focuses on glucose metabolism is on discovering alternative non-pharmacological treatments for diabetes in humans, which could have significant implications for developing feed additives that enhance animal performance by promoting insulin-dependent glucose metabolism." (PMID 39339244, 2024). "Type 2 diabetes mellitus (T2DM) is the most common type of diabetes mellitus (DM), whose pathogenesis is that the cells in the body are not sensitive to insulin, meaning they do not respond to insulin." (PMID 38562414, 2024). "Education and management of children with new-onset or established diabetes mellitus (DM) requiring insulin initiation do not always require hospitalization." (PMID 39568636, 2024). "Taking as a priority comprehensive studies of epigenetics and its relationship with diabetes, more attention could be paid to the morphology of pancreatic islets, the metabolic pathways of insulin, and how they are affected by the presence or absence of epigenetic changes." (PMID 38397953, 2024). "Therefore, individuals who manage diabetes without insulin might have a metabolic environment more conducive to gaining muscle mass when engaged in resistance training." (PMID 38919474, 2024). "Insulin-positive β-cells were detected abundantly in the center of the islet of Langerhans of the normal rats, while in islets of the diabetic rats, insulin-positive β-cells were found very few to none in number, and this was due to diabetes induction and β-cell destruction using STZ." (PMID 39337311, 2024). "The patients in this study were using a smart insulin pen (NovoPen 6) in conjunction with CGM, but still experienced missed basal insulin doses; therefore, the addition of a smart insulin pen alone may not be sufficient to ensure 100% adherence to diabetes therapies among patients with T1D." (PMID 35775735, 2024). "Higher NEFA levels may also be a marker of impaired action of insulin to suppress lipolysis (insulin resistance), although this seems less likely because the patients with IPF had lower circulating glucose levels and a smaller proportion had diabetes than the controls." (PMID 38273290, 2024). "Diabetes includes insulin-dependent or type 1 diabetes (T1D), attributed to a lack of insulin, representing 5% of the diabetes cases, and non-insulin-dependent or type 2 diabetes (T2D), characterized by an insensitivity or resistance to insulin, representing 95% of the diabetes cases." (PMID 38279738, 2024). "Interestingly, prospective cohort studies have reported that NT-proBNP levels are lower in individuals with obesity or diabetes, suggesting that obesity and low insulin sensitivity may have negative effects on the neurohormonal homeostasis provided by the NP." (PMID 39097697, 2024). "We performed this subgroup analysis for two reasons: 1) to eliminate the potentially confounding factor of using other diabetic medications such as metformin or insulin, and 2) we did not have data on the severity of diabetes such as hemoglobin A1c which may be an additional confounding factor." (PMID 39318780, 2024). "Clinical trials in obese people with and without diabetes have shown that GLP-1RAs, the most recent anti-obesity medications approved for human use, are associated with beneficial weight-loss and metabolic improvements inclucing lower TC, TG, LDL, FPG, and insulin." (PMID 38762728, 2024). "More participants in the insulin group were unaware of the difference between eye tests for spectacles and diabetic-related eye changes (64.7%) compared to the non-insulin group (44.8%), suggesting a lack of knowledge and awareness about diabetes and its complications in the eye." (PMID 39587498, 2024). "Also, the lack of insulin in patients with diabetes may contribute to enhanced platelet activation as insulin binds to the insulin receptor (IR) located on the platelet surface and activates insulin receptor substrate 1 (IRS-1) via tyrosine phosphorylation." (PMID 38398275, 2024).